CD4 (CD4 molecule)
Diseases named in the same sentence as CD4 in open-access papers (continued):
Sharing a sentence is not in itself a finding about the gene and the disease.
liver cancer (continued). "Regarding the genealogical differentiation of CD4+ T-cells, the scRNA-seq data indicated that naive CD4+ T-cells transformed into Treg in primary liver cancer TIME, which may be correlated with macrophages." (PMID 38649887, 2024). "Immunofluorescence analysis of liver cancer samplesshowed a significant increase in CD4+ and CD8+ T cell infiltration into the tumor and a modifying effect on thetumor microenvironment, such as increased MVD and CD8/Treg ratio,in the combination therapy group of anti-PD-1 antibody and STR-V-53." (PMID 39416967, 2024). "CD3+ T cells, CD4+ T cells and CD4+/ CD8+ T were decreased in the liver cancer patients." (PMID 36765353, 2023). "Liver cancers also show high levels of overall T cells (CD4++CD8++Treg cells)." (PMID 36612149, 2022). "Surprisingly, the expression of ZIC2 mRNA revealed a significant positive correlation with tumor purity, and with B cell, CD8+ T cell, CD4+ T cell, macrophage, neutrophil, and dendritic cell infiltration in the immune microenvironment of liver cancer (Timer database, Cor > 0, P<0.001)." (PMID 33439969, 2021). "The relationship between CD4+CD25+CD127LowTregs and TGF-β1 and IL-10 levels, and the analysis of the differences in immune status of patients with liver cancer are expected to provide valuable and diagnostic reference data for clinical treatment, the disease course, and prognosis of liver cancer." (PMID 32218692, 2020). "Our analyses also demonstrated the protective role of CD3 on naive CD8+ T cells and CD3 on naive CD4+ T cells in mediating the causality between anilide medications and liver cancer, inspiring the idea of combining anilides with CD3-related immunotherapy for liver cancer treatment." (PMID 39062110, 2024). "In liver cancer, the activation of CD8+ T cells is related to the number of DCs and also CD4+ T cells." (PMID 40136652, 2025). "The Cancer Genome Atlas (TCGA) liver cancer dataset was used to stratify patients into high (hi) and low (lo) expression groups based on the expression levels of CD3, CD4, and CD8 markers, and their OS was compared." (PMID 40361474, 2025). "Recent research in CD4+ T cells has shown that MATR3, as a key regulator of CD4+ T cell function in a liver cancer model, recruits the ARID1A-containing cBAF complex to enhance chromatin accessibility at the TOX promoter region, thereby exacerbating CD4+ Tex." (PMID 40342423, 2025). "In our study, we observed a positive correlation between CXCL3 expression and infiltration of macrophages, neutrophils, B cells, CD4-positive T cells, CD8-positive T cells, and dendritic cells in liver cancer tissues." (PMID 41259383, 2025). "Activated CD4 T cells can regulate immune surveillance in HCC, thereby inhibiting the development of liver cancer." (PMID 40255404, 2025). "And protective causality for the impact of CD3 on naive CD8+ T cells (IVW OR = 0.7530, 95% CI = 0.5997 to 0.9456, p < 0.05) and CD3 on Naive CD4+ T cells (IVW OR = 0.8041, 95% CI = 0.6469 to 0.9996, p < 0.05) on liver cancer were revealed." (PMID 39062110, 2024). "Its expression inversely correlated with the infiltration of CD4+, CD8+, CD45RO+ T lymphocytes in liver cancer and inhibits effective anti-tumor immunity." (PMID 39085878, 2024). "It has been found that the proliferation of CD8+ CTLS in liver cancer depends on cell triplets formed by progenitor cytlike CD8+T cells with DC cells and CD4+ helper T cells." (PMID 39816386, 2024). "Next, the TIMER online tools explored six types of immune infiltration cells (B cell, CD4+ T cell, CD8+ T cell, macrophage, neutrophil, and dendritic cell) in liver cancer." (PMID 36741874, 2023). "Interestingly, our data showed that the DTL expression showed positive associations with most markers of activated T cells, specifically CD8+/CD4+ T cells, in liver cancer, suggesting that HCC tumors with the overexpression DTL phenotype might potentially be a hot tumor." (PMID 35392073, 2022).
liver cancer (continued). "An analysis of single-cell sequencing data of liver cancer immune cells found that lncRNA MIAT was significantly enriched in Foxp3+ CD4+ T cells, PDCD1+ CD8+ and GZMK+ CD8+ T cells, which mediated the immune escape of liver cancer." (PMID 36092924, 2022). "In one SR on liver cancer, it showed beneficial effects of add-on with Aidi injection on ORR, KPS scores, survival rate, and immune function assessed by CD3 and CD4 compared to transarterial chemoembolization (TACE) treatment alone." (PMID 34025425, 2021). "Before liver cancer treatment, the TGF-β1 and IL-10 concentrations were positively correlated with the percentage of CD4+CD25+ CD127lowTregs in patients with HCC respectively ((r = 0.526, P = 0.017; r = 0.546, P = 0.013)." (PMID 32218692, 2020). "A large number of studies have found that CD4+CD25+ Treg cells can be detected in peripheral blood and tumor-infiltrating lymph nodes of patients with gastric cancer, liver cancer, breast cancer, and other cancers." (PMID 33204731, 2020). "The correlation between regulatory T cells and TGF-β1 and IL-10 has been widely reported, and the results of this study show that CD4+CD25+CD127low Tregs were positively correlated with TGF-β1 and IL-10 before and after treatment of liver cancer." (PMID 32218692, 2020). "After liver cancer treatment, the TGF-β1 and IL-10 concentrations were positively correlated with the percentage of CD4+CD25+ CD127lowTregs in patients with HCC respectively (r = 0.543, P = 0.013; r = 0.789, P=0.000)." (PMID 32218692, 2020). "Since NAFLD affects intrahepatic CD4+ T cells, the question of how NAFLD influences the efficacy of immunotherapy for liver cancer needs to be evaluated." (PMID 29795111, 2018). "However, an excessive accumulation of linoleic acid in NAFLD leads to a selective decrease in CD4+ T cells, which contributes to the progression of NAFLD to liver cancer." (PMID 40122853, 2025). "Moreover, the expression of SLC10A3 protein is correlated with stromal CD4 T cells, CD20 B cells, macrophages, PDCD1 (PD-1) and CD274 (PD-L1) expression, indicating a potential regulatory role in liver cancer immunotherapy." (PMID 38178258, 2024). "It was noted that memory CD4 T cells (CD4+CD69+) were enriched in liver cancers with low clonality, while proliferative pre-exhausted CD4 T cells (CD4+MKI67+CXCL13+) were enriched liver cancers with high clonality and a major source of cytokines and chemokines." (PMID 36980203, 2023). "This is relevant as CD4+ Th1 lymphocytes, through production IFN-γ, enhance anti-tumoral response in HCC and accordingly, a significant decrease of CD4+ Th1-cells in patients with liver cirrhosis and HCC has been reported, highlighting their importance in liver cancer biology." (PMID 33406763, 2021). "Lymphoid regulatory cells participate in monitoring internal immune homeostasis, the negative functional ones including FOXP3+CD25+CD4+ regulatory T cells (Treg) and regulatory B cells (Breg) possess inhibitory roles on antitumor immunity in liver cancer." (PMID 34372912, 2021). "In summary, CEP55 is overexpressed in liver tumor tissues compared to normal liver tissues and CEP55 overexpression is related to dismal prognosis and increased immune infiltration levels of B cells, CD4+ T cells, CD8+ T cells, macrophages, neutrophils, and dendritic cells in liver cancer." (PMID 32337246, 2020). "B cell naive, B cell, T cell CD4+ memory resting, and T cell CD4+ were significantly different in recurrence versus non-recurrence liver cancer samples and were found to be negatively correlated with the risk scores predicted by the constructed model by correlation analysis." (PMID 34956309, 2021). "Additionally, it should be noted that 40% of HIV positive patients with a nadir CD4+ cell count of less than 200 cells/ml have a potential of developing non-infectious co-morbidities (NICMs) including liver cancer." (PMID 30607173, 2018).
liver cancer (continued). "In addition, the high expression of ERGIC3 was positively correlated with the infiltration of B cells, macrophage, myeloid dendritic cells, CD4+ T and other immune cells, suggesting that ERGIC3 may affect the prognosis of liver cancer patients by raising the abundance of infiltrating immune cells." (PMID 35602902, 2022). "On the other hand, presence of CD4 tumor-specific epitopes combined with a lack of CD8 tumor-specific epitopes neither led to CD4, nor to CD8 T cell responses, showing the mutual dependence that is necessary for efficient liver cancer immune surveillance." (PMID 34209393, 2021). "First, we systematically investigated 28 immunological features based on intra- and peri-tumoral tissues in liver cancer that are not confined to the commonly used CD3, CD4, CD45RO, or CD8." (PMID 31164128, 2019).
malnutrition (107 papers, 2006 to 2026). Inadequate nutrition resulting from poor diet, malabsorption, or abnormal nutrient distribution. "Previous research has established that malnutrition and low CD4 counts are risk factors for TB in HIV-positive individuals." (PMID 38995935, 2024). "Our results indicate that malnutrition increases VL susceptibility due to defective activation and expansion of CD4+ IFNγ+ T cells, decreased iNOS expression, and reduced hepatic granuloma formation, which is attributable to increased IL-10 production." (PMID 39527629, 2024). "Malnutrition impairs cellular immunity by causing atrophy of the thymus, lymph nodes, and tonsils, resulting in decreased CD4 and secretory immunoglobulin A, and weakened delayed hypersensitivity and phagocytosis." (PMID 35775061, 2022). "We report here a case of neuromeningeal cryptococcosis associated with pulmonary tuberculosis and malnutrition in an HIV-seronegative patient with a CD4 count of 750/mm3, to highlight some particularities opposed to certain literatures." (PMID 36815177, 2022). "Diarrhea can persist for several months in patients with CD4+T-lymphocyte counts less than 50 to 100 cells/mm3, resulting in severedehydration, weight loss, malnutrition, extended hospitalization, and even death." (PMID 32037854, 2020). "Diarrhea can persist for several months in patients with CD4+T-lymphocyte counts less than 50 to 100 cells/mm3, resulting insevere dehydration, weight loss, malnutrition, prolonged hospitalization,and even death." (PMID 32037854, 2020). "Studies also found that malnutrition was associated with lower CD4 count, and it tends to decrease CD4 counts recovery and predisposes patients to early death." (PMID 29854730, 2018). "Future studies, which include viral load monitoring, would help to clarify the mechanism by which malnutrition and low BMI are associated with low CD4 counts among individuals receiving ART in Senegal." (PMID 26529509, 2015). "We found that severe food insecurity is associated with lower attendance at clinic appointments and lower adherence to antiretroviral therapy, and that malnutrition is associated with lower CD4 cell counts." (PMID 26529509, 2015). "In contrast, the association of the Mtb specific CD4+ response with treatment was marginal, and affected by underlying malnutrition." (PMID 24324704, 2013). "Studies reported that leptin deficiency is correlated with nutritional deprivation or malnutrition, which affects the innate and acquired immunity of the host, by decreasing the number of T lymphocytes, CD4 + and CD8 +, thus increasing the incidence of infections and the mortality rate." (PMID 33907162, 2021). "Lower CD4 counts has been associated with moderate to severe malnutrition." (PMID 32549993, 2020). "Malnutrition tends to decrease CD4 recovery and predisposes patient to early death." (PMID 27688793, 2016). "Malnutrition was associated with lower CD4 recovery and greater hazard of death." (PMID 27688793, 2016). "Malnutrition was associated with lower CD4 counts (p = 0.01)." (PMID 26529509, 2015). "Malnutrition was associated with lower CD4 cell counts (p = 0.01)." (PMID 26529509, 2015). "We found that malnutrition was associated with lower CD4 counts." (PMID 26529509, 2015). "In fact, using a murine model of malnutrition, it was observed that the thymic atrophy is largely due to massive thymocyte death combined with decreased thymocyte proliferation primarily due to the loss of immature CD4+CD8+ double positive T cells." (PMID 25535967, 2014). "Patients who have taken ART drugs for <12 months may have adverse drug events, existing coinfections and/or comorbidities, severely low hemoglobin, a low body mass index (severe malnutrition), and/or very low CD4 counts, which may cause them to miss the scheduled appointment." (PMID 38078055, 2023). "However, few studies have investigated the association of malnutrition and CD4 response." (PMID 22216334, 2011).
malnutrition (continued). "Case numbers were too small to study the impact of CD4 count on nasal signatures, and other covariates that impact gene expression, like malnutrition and TB infection via TST or IGRA status, were unavailable." (PMID 41542684, 2026). "Anxiety was linked to malnutrition (AOR=1.80, p=0.04) and low CD4 count (≤200 cells/mm3; AOR=0.20, p=0.02)." (PMID 41798574, 2026). "During malnutrition, the number of naïve T cells decreased in the lymph nodes and increased in the bone marrow, where naïve CD4+ T cells experienced less apoptosis than controls." (PMID 41992943, 2026). "Overall, naïve CD4+ T-cell migration to the bone marrow during malnutrition is intrinsic, requires sensitivity to glucocorticoids, and likely contributes to naïve T-cell preservation in mice." (PMID 41992943, 2026). "T-cell sensitivity to glucocorticoids was required for elevated expression of CXCR4 and CCR7 in naïve CD4+ T cells during malnutrition." (PMID 41992943, 2026). "Our study also corroborates findings from South Africa, where advanced immunosuppression (CD4 < 100 cells/μL) and malnutrition were key predictors of poor outcomes." (PMID 41150353, 2025). "Other factors are also associated with the negative results of T-SPOT.TB, leading to uncertainty in the detection, such as advanced age, malnutrition, low CD4 + T-cell levels, and the use of immunosuppressive agents." (PMID 39838164, 2025). "Malnutrition alone can have a detrimental impact on the cluster of differentiation-four (CD4+) T cells, resulting in an impaired B-cell response." (PMID 39114120, 2024). "Due to a decrease in activated CD4+ T cells, the effect of malnutrition on IL-2 production, as IL-2 is important for T cell proliferation was determined." (PMID 32033605, 2020). "The reduced numbers of activated effector CD4+ T cells in malnourished mice was expected, as studies suggest that malnutrition has detrimental effects on immune response." (PMID 32033605, 2020). "Given that Moringa is rich in protein and the current study showed that it increases CD4+ T cell numbers and proportions, Moringa’s potential to remediate the immune suppressive effects of malnutrition was determined." (PMID 32033605, 2020). "Model 1 includes main effect adjustments for time since ART initiation, age, gender, baseline weight-for-age, baseline CD4%, baseline malnutrition indicator, baseline WHO stage, centre, and primary carer." (PMID 32645021, 2020). "PLWHA who had CD4 count less than 350 cells/μl had significantly higher malnutrition (27.6%) compared with PLWHA who had CD4 count greater than 350 cells/μl (10.3%) (P value = 0.003)." (PMID 29854730, 2018). "A previous report documented that malnutrition reduced the concentrations of immunoglobulins, and CD4 and CD8 T-cells and natural killer cells among patients with TB." (PMID 29944658, 2018). "In this cross-sectional study we explored potential associations between malnutrition, BMI, and HIV measures and outcomes, including time since diagnosis, WHO stage, time on ART, ART regimen, adherence, and CD4 count." (PMID 26529509, 2015). "Among 240 children enrolled (mean age 7.7 years, 54.6 % males), median CD4 was 25 %, 19.2 % had advanced disease, 45.5 % had malnutrition, and 43.3 % were on antiretroviral treatment (ART) at baseline." (PMID 26482352, 2015). "This suggests that immune mechanisms involving some aspects of T cell function are affected by malnutrition (CD4 cells are a subset of T cells)." (PMID 25475887, 2014). "Physiological stress resulting from infections, trauma, surgery, alcoholism, malnutrition, and/or pregnancy results in a substantial depletion of immature CD4+CD8+ thymocytes." (PMID 24416377, 2014). "The Mtb specific CD4+ T cell response at baseline was significantly reduced in subjects with moderate to severe malnutrition (BMI≤17; n = 14) compared with subjects with a BMI>17 (n = 34; p = 0.0067)." (PMID 24324704, 2013).